MTF1 (metal regulatory transcription factor 1)
Diseases named in the same sentence as MTF1 in open-access papers (continued):
Sharing a sentence is not in itself a finding about the gene and the disease.
tumor (continued). "In tumor tissues, the abundance of CDKN2A and MTF1 were higher, as well as the levels of DLD, FDX1, GLS, LIPT1 and PDHB were down-regulated." (PMID 37662947, 2023). "The results revealed that LIAS, DLAT, PDHA1, and CDKN2A were significantly upregulated in LUAD tumors compared to normal tissues, while ATP7B, SLC31A1, FDX1, MTF1, and GLS were significantly downregulated in tumor tissues." (PMID 36983664, 2023). "The lncRNAs affect the process of tumor metastasis by regulating the cell cuproptosis sensitivity such as CDKN2A, GLS and MTF1." (PMID 37745054, 2023). "Future work will be required to investigate the relationship between MTF-1 and FOS/JUN in tumor progression." (PMID 36980293, 2023). "This called for more practical testing, so in the Taizhou cohort, we performed qRT-PCR experiments on 127 tumor tissues and their corresponding normal samples to obtain the expression of genes (FDX1, LIAS, PDHB, and MTF1)." (PMID 36212447, 2022). "Subsequently, we detected the expression of these CRGs in tumor and normal samples and found that 6 genes, FDX1, LIAS, DLD, DLAT, PDHB and MTF1, were significantly downregulated in tumors, while 2 genes, GLS and CDKN2A, were significantly upregulated." (PMID 36246586, 2022). "The expression of MTF1, NLRP3, and SLC31A1 was positively related with ImmuneScore, StromalScore, and ESTIMATEScore in almost all types of tumor, whereas ATP7B, DLAT, DLD, LIAS, PDHA1, and PDHB were significantly negatively correlated with the scores." (PMID 36387247, 2022). "We found that LIAS and CDKN2A were significantly upregulated in tumor samples, and FDX1, DLD, DLAT, PDHA1, PDHB, MTF1, and GLS were significantly downregulated in tumor samples." (PMID 36531222, 2022). "CDKN2A, GLS, LIPT1, and PDHA1 were up-regulated in tumor samples, and FDX1, DLD, MTF1 were down-regulated in tumor samples." (PMID 36176287, 2022). "Of the six cuprotosis-related genes included in the signature, we found FDX1, LIAS, DLAT, MTF1, and GLS to be differentially expressed between tumor and normal tissues at the protein level." (PMID 36247012, 2022). "It was worth mentioning that five of them were downregulated in tumor samples, including DLAT, MTF1, PDZD4, FDX1, and RPS25, and the rest of the genes were all upregulated." (PMID 36010978, 2022). "Additionally, cisplatin treatment further inhibited MTF1 KO HEY and HEC1A xenograft tumor growth compared to its inhibitory effect on wild-type tumors." (PMID 39920630, 2025). "MTF1 displayed strong or medium staining in normal kidney, testis and colon tissues, and weak or negative staining in the corresponding tumor tissues." (PMID 37380924, 2023). "Interestingly, MTF1, PDHB and GLS were reported to be highly expressed in other tumor types, while in our study, we found that these genes were strongly associated with good prognosis." (PMID 36620594, 2022). "In the Human Protein Atlas database, the expressions of GLS, MTF1 and PDHA1 in tumor tissues were lower compared with those in normal tissues, while the expressions of DLAT and PDHB were significantly higher in tumor tissues compared with those in normal tissues." (PMID 36620594, 2022). "Furthermore, EGCG also down-regulated the expression of ATP7B and MTF1 in tumor tissues without affecting CTR1 expression." (PMID 40136640, 2025). "Moreover, further analysis was made to investigate the mRNA expression level of CRGs between normal and CRC samples, and we found that the expressions of FDX1, DLD, DLAT, PDHB, and MTF1 were significantly decreased, whereas LIPT1, GLS, and CDKN2A were significantly upregulated in tumor samples." (PMID 37006250, 2023). "Besides, FPN could also be regulated by hypoxia inducible factor 2 (HIF2α), nuclear factor erythroid (Nrf2), metal regulatory transcriptioan factor 1 (MTF1), and myeloid zinc finger 1 (MZF1) at the transcriptional level in macrophages and tumor cells." (PMID 27768596, 2016).
tumor (continued). "In addition, our study found that EGCG down-regulated the expression of MTF1 and ATP7B, but was not affected by copper, that is, EGCG treatment alone was capable of down-regulating the expression of ATP7B without causing cuproptosis in cells or tumor tissues." (PMID 40136640, 2025). "Of the six cuprotosis-related genes, we found that FDX1, LIAS, DLAT, MTF1, and GLS were differentially expressed between tumor and normal tissue and were upregulated in normal tissue." (PMID 36247012, 2022). "We found that five cuprotosis molecules, DLAT, PDHA1, FDX1, GLS and CDKN2A, were significantly different between paired tumour and adjacent non-tumour samples from the TCGA-STAD cohort, and LIAS, DLD, DLAT and MTF1 were significantly different among the four pathologic T categories 1–4." (PMID 36895378, 2023).
cancer (33 papers, 2012 to 2026). A tumor composed of atypical neoplastic, often pleomorphic cells that invade other tissues. "Here we uncovered that MTF1 had a considerable mutation rate in a variety of malignant tumors, and some of them were correlated with prognosis and other indicators." (PMID 39308676, 2024). "Our findings revealed dysregulation of MTF1 in pan-cancer along with its correlation with certain clinicopathological features, suggesting its diagnostic and prognostic value for multiple cancer types." (PMID 39308676, 2024). "Although the aberrantly expressed MTF1 has been detected in several cancers, its potential biological functions and underlying mechanisms have not been well investigated." (PMID 37380924, 2023). "In addition, we analyzed the association between MTF1 expression and immune subtypes, immune cell infiltration, and immune-related biomarkers in a variety of malignant tumors." (PMID 39308676, 2024). "Taken together, this pan-cancer analysis of MTF1 has implicated that MTF1 could play an essential role in the progression of various human cancers." (PMID 37380924, 2023). "According to these results downloaded from the CancerSEA website, we found that MTF1 could be essential in the regulation of cancer-associated biological functions." (PMID 37380924, 2023). "The mutation profiles of MTF1 in pan-cancers were analyzed using cBioPortal." (PMID 37380924, 2023). "Exploring the underlying mechanisms and biological functions of MTF1 could provide novel strategies for clinical diagnosis and therapy of cancers." (PMID 37380924, 2023). "In addition, the ROC curve indicated the diagnostic role of MTF1 in pan-cancer." (PMID 39308676, 2024). "Because MTF1 knockout could enhance cell sensitivity to cuproptosis, targeting MTF1 and its associated signaling pathway could be a potential treatment strategy for cancer." (PMID 38918694, 2024). "Our data show that the MTF1-dependent heavy metal response induces cancer cell resistance to platinum-based compounds both in vitro and in vivo." (PMID 39920630, 2025). "Our data confirmed that the expression of MTF1 target genes correlates with poor overall survival in patients with breast, ovarian, and head and neck cancers." (PMID 39920630, 2025). "To assess the broader impact of our findings, we utilized different cancer models to examine the Hippo-MTF1 pathway-mediated heavy metal response in platinum-based chemotherapy." (PMID 39920630, 2025). "Our data demonstrate that platinum-based drugs activate MTF1 and induce the expression of downstream heavy metal response genes in various cancer cell lines." (PMID 39920630, 2025). "MTF1 regulates the proliferation of normal and cancer cells by activating downstream target genes and then participates in the formation and progression of tumors." (PMID 38943058, 2024). "Through a widely used ssGSEA method, we found that MTF1 was significantly negatively correlated with pDC and positively correlated with helper T cell and Tcm in most cancers." (PMID 39308676, 2024). "We found that the expression of MTF1 was significantly positively correlated with Tcm and T helper cells, and negatively correlated with pDC in most cancers." (PMID 39308676, 2024). "In the present study, the expression profiles and clinical significance of MTF1 in pan-cancer were revealed." (PMID 39308676, 2024). "To understand the probable role of MTF1 in specific cancers better, we performed the GSEA analysis in four tumors with statistical differences in survival analysis, namely KIRC, LGG, LUSC, and HNSC." (PMID 39308676, 2024). "Given that MTF1 is dysregulated in a variety of cancers and its probable role in immune and cell death, many problems remain to be investigated in the future." (PMID 39308676, 2024). "In this study, we conducted a series of bioinformatics analyses to investigate the clinical significance and potential functions of MTF1 across various types of cancer." (PMID 39308676, 2024).
cancer (continued). "Subsequent in vitro assays indicated that MTF1 reduced the sensitivity of cancer cells to cuproptosis." (PMID 39308676, 2024). "In conclusion, MTF1 is likely to be a potential biomarker for diagnosis and prognosis of a variety of cancers." (PMID 39308676, 2024). "Second, this study failed to give a more specific explanation for the different expression and survival of MTF1 in pan-cancer." (PMID 39308676, 2024). "Further analysis showed that there was a significant positive correlation between CNV and MTF1 expression in most cancer species (|correlation| > 0.3 and FDR < 0.05)." (PMID 39308676, 2024). "Given the critical role of regulatory cell death in cancer treatment resistance 15, the relationship between MTF1 and cuproptosis and the role of MTF1 in cancer and immunity need to be further clarified." (PMID 39308676, 2024). "In this study, a series of enrichment analyses were conducted to explore the functions of MTF1 in cancer." (PMID 39308676, 2024). "To explore the expression of MTF1, we analyzed the mRNA expression data of 33 kinds of cancers from the GTEx and TCGA databases." (PMID 39308676, 2024). "For example, TIMER2.0, TNMplot and GEPIA2.0 were employed to analyze the expression values of MTF1 in pan-cancer." (PMID 37380924, 2023). "In order to further explore the relationship between the immune cell infiltration and MTF1 expression in TCGA pan-cancer, several algorithms (TIMER, EPIC, MCPCOUNTER, CIBERSORT, CIBERSORT-ABS, QUANTISEQ and XCELL) were employed in TIMER2.0." (PMID 37380924, 2023). "To sum up, through a series of pan-cancer analysis, we investigated the expression, prognosis, genetic alteration and methylation profiles of MTF1 in various cancers." (PMID 37380924, 2023). "In our study, we applied the CancerSEA to explore MTF1 expression at single cell levels across some cancers." (PMID 37380924, 2023). "Meanwhile, the CPTAC from UALCAN database also showed MTF1 protein levels in multiple types of cancers." (PMID 37380924, 2023). "And this article would provide a new strategy for the MTF1-based survival prediction in several cancer patients." (PMID 37380924, 2023). "The down-regulated protein levels of MTF1 in these cancers were consistent with the transcriptional levels of MTF1 obtained from the TNMplot." (PMID 37380924, 2023). "Here, we employed the TCGA dataset and some other bioinformatics tools to explore the regulation roles of MTF1 in a variety of cancers." (PMID 37380924, 2023). "We not only explored the expression levels of MTF1 in cancers, but also investigated the survival values, genetic alteration, methylation and enriched signaling pathways." (PMID 37380924, 2023). "The CancerSEA database was employed to investigate the expression levels of MTF1 at single cell level in human cancers." (PMID 37380924, 2023). "In this study, we conducted the comprehensive analysis to evaluate the profiles of MTF1 in pan-cancer." (PMID 37380924, 2023). "Here, we used several algorithms from TIMER2.0, such as TIMER, EPIC, MCPCOUNTER, CIBERSORT, CIBERSORT-ABS, QUANTISEQ and XCELL, to analyze the relationship between immune cell infiltration and MTF1 expression in pan-cancer." (PMID 37380924, 2023). "Several seminal studies have delineated the unique functions of MTF1 in the development of various diseases, especially like cancers." (PMID 37380924, 2023). "GEPIA2.0, Kaplan–Meier plotter and cBioPortal were also used to explore the roles of MTF1 in cancer prognosis." (PMID 37380924, 2023). "Prognostic analysis for OS, DSS, and PFS revealed that hypomethylation of DLAT, FDX1, MTF1, NLRP3, and PDHA1 was associated with low survival in most cancers, whereas hypermethylation of FDX1 and PDHB was associated with low survival in UVM(P < 0.05)." (PMID 36387247, 2022). "(2020) study, our present report highlights MTs and MTF1 as such candidate predictive biomarkers, which are upregulated and vary considerably among the patients as well as different cancer types." (PMID 34632694, 2022).
cancer (continued). "We found that the expression of PDHA1, GLS, DLAT, PDHB and MTF1 were differed between cancer and paracancer." (PMID 36620594, 2022). "ZEB1, HES1, NR6A1, PATZ1, PAX4 and MTF1—have a reported oncogenic role in cancer types other than HCC." (PMID 33541355, 2021). "In relation to cancer, both MTF-1 and MT are over-expressed in radiation resistant tumors, perhaps supporting the importance of zinc acquisition for cancer growth." (PMID 22852056, 2012). "Indeed, we found that activation of the Hippo pathway inhibits MTF1, thereby sensitizing cancer cells to platinum-based chemotherapy." (PMID 39920630, 2025). "In addition, targeting either the Hippo pathway or LATS-induced MTF1 S152 phosphorylation protected cancer cells from cisplatin treatment, while pharmacological activation of the Hippo pathway enhances cisplatin sensitivity." (PMID 39920630, 2025). "Therefore, this study revealed the comprehensive role of MTF1 in pan-cancer and provided a potential predictor for immune infiltration and expression of immune-related biomarkers in some types of cancers." (PMID 39308676, 2024). "Collectively, these findings indicate that MTF1 could be a crucial factor in the progression of various human cancers." (PMID 38918694, 2024). "Therefore, we hope to have a deep and comprehensive understanding of the role of MTF1 in cancer and immunity." (PMID 39308676, 2024). "CDKN2A is highly expressed in almost all cancer types, while MTF1 is lowly." (PMID 38573998, 2024). "As the role of cuproptosis in cancer treatment is gradually revealed 50, the cuproptosis-suppressive molecule MTF1 may be a potential therapeutic target for some cancers." (PMID 39308676, 2024). "By analyzing the methylation and CNV of the MTF1 gene in pan-cancer, we may provide a potential explanation for the abnormal expression of MTF1 in different cancer species." (PMID 39308676, 2024). "Meanwhile, DiseaseMeth version 2.0 also depicted the levels of MTF1 methylation in various cancers." (PMID 37380924, 2023). "To investigate whether MTF1 plays an important role in different types of cancers, we have conducted a pan-caner analysis of MTF1 and evaluated its underlying mechanisms." (PMID 37380924, 2023). "In addition, the diverse expression values and prognostic profiles in multiple cancers predicts the highly complex roles of MTF1 in human cancers." (PMID 37380924, 2023). "These explorations have elucidated that MTF1 could play a vital part in the progression of various cancers." (PMID 37380924, 2023). "Thus, the underlying molecular mechanism of MTF1 should be further evaluated to demonstrate the functional roles of MTF1 in cancers." (PMID 37380924, 2023). "Meanwhile, we explored the roles of MTF1 on the posttreatment prognosis of cancer patients." (PMID 37380924, 2023). "In contrast, FDX1 and MTF1 expression in most cancers were lower than paired normal tissues." (PMID 36518756, 2022). "Overall, our study highlights that MTF1 may serve as a promising biomarker for prognosis assessment and a potential therapeutic target for more effective treatment strategies against various cancers." (PMID 39308676, 2024). "However, reports on MTF1 in most kinds of cancers are scarce so far." (PMID 39308676, 2024). "In this study, by analyzing MTF1 mRNA levels in paired and unpaired samples, we found that MTF1 expression in most tumors was different from that in normal tissues and closely related to cancer severity and prognosis, pathological stage, histological grade, and the outcome of initial treatment." (PMID 39308676, 2024). "In addition, we applied HPA database to further explore the protein levels of MTF1 in the cancers." (PMID 37380924, 2023). "In addition, we used the GEO database to analyze the expression profiles of MTF1 in some cancers." (PMID 37380924, 2023).
cancer (continued). "We found telomere maintaining genes (TERF2, CTC1, and ACD), genes involved in zinc homeostasis (MTF1 and SLC30A9), transcription elongation factor complex components (ICE1, ICE2, ELL), and BCL6 corepressors (BCOR, BCORL1) uniquely invoked in TNBC cancers." (PMID 40700427, 2025). "CDKN2A, MTF1, LIAS, GLS, FDX1 and CDKN2A have been highlighted as the regulators of cuproptosis, with its expression correlating with poor survival outcomes in cancers." (PMID 41158129, 2025). "Moreover, a recent study reported that LATS, a kinase of the Hippo pathway that governs organ size and cancer development, could disrupt heavy metal homeostasis and reduce cellular protection by phosphorylating and inhibiting MTF1, suggesting a possible role for LATS in cuproptosis." (PMID 38918694, 2024). "We analyzed the relationship between MTF1 expression and OS, PFS, and DSS in different types of cancer to evaluate its prognostic value." (PMID 39308676, 2024). "However, no obvious association could be identified between MTF1 levels and pathological stages in other cancers." (PMID 37380924, 2023). "Metal regulatory transcription factor 1 (MTF1) has been reported to be correlated with several human diseases, especially like cancers." (PMID 37380924, 2023). "And we found that MTF1 expression had a positive correlation with the expression levels of SLC31A1 (R = 0.17, p < 0.001), SLC11A2 (R = 0.33, p < 0.001) in pan-cancer." (PMID 37380924, 2023). "In total, 14 DECRs were identified, of which six regulators (MTF1, DLST, NLRP3, DBT, FDX1, and DLD) were downregulated in cancer tissues." (PMID 36672336, 2023). "Most cancers show significantly lower mRNA levels in FDX1, DLD, DLST, LIAS, GLS, DBT, MTF1, and PDHB." (PMID 36209249, 2022). "We also identified potential transcriptional factors with known oncogenic roles in HCC, e.g. ZEB1, or in other cancer types, e.g. HES1, NR6A1, PATZ1, PAX4 and MTF1, in GE1-HCC." (PMID 33541355, 2021). "Since the role of MTF1 in pan-cancer has not been clarified, we analyzed the correlation between the expression of MTF1 and pathological stage, histologic grade, and primary therapy outcome." (PMID 39308676, 2024). "The correlation calculated for all paired samples (33 cancer types) revealed that of the 10 cuprotosis molecules, six (DLAT, DLD, MTF1, CDKN2A, GLS and FDX1) may be negatively regulated by many miRNAs." (PMID 36895378, 2023). "Moreover, the heatmap confirmed the positive relationship between MTF1 and SLC31A1 and SLC11A2 in almost all cancer types." (PMID 37380924, 2023). "patients with high expression of CDKN2A, MTF1, and GLS had worse prognoses, suggesting that CDKN2A, MTF1, and GLS might promote the proliferation of cancer cells." (PMID 36159561, 2022).